VDR (vitamin D receptor)
Diseases named in the same sentence as VDR in open-access papers (continued):
Sharing a sentence is not in itself a finding about the gene and the disease.
inflammation (5 papers, 2013 to 2023). Aberrant reaction of the microcirculation characterized by movement of fluid and leukocytes from the blood into extravascular tissues. "VDR has anti-inflammatory effects, and the VDR/NLRP3 (nucleotide-binding oligomerization domain-like receptor family pyrin domain containing 3) pathway has been suggested to be linked to pancreatic inflammation." (PMID 37808100, 2023). "Th-1 and 17 exacerbate the immune response in CD chronic inflammation, and it is clear that the VDR may suppress the CD associated inflammatory response." (PMID 24084050, 2013). "In conclusion, this study showed that the VDR expression decreased in the islets of Langerhans during pancreatic inflammation and demonstrated the expression of CYP24A1 and CYP27B1 in canine pancreases for the first time." (PMID 37808100, 2023). "Meanwhile, administration of microbiota-derived butyrate elevated the expression of VDR and relieved inflammation in DSS-treated mice, thus showing the bidirectional effects between gut microbiota and VDR in intestinal inflammation." (PMID 34579027, 2021).
myopathy (5 papers, 2013 to 2019). A disease of the muscle in which the muscle fibers do not function properly. "The study showed a four times greater risk of myopathy in individuals homozygous for the C allele in the VDR polymorphism TaqI (rs731236) (RR 4.37, 95 % CI: 1.9–10.1, p <0.01) and in patients with 25OHD levels <50 nmol/L (RR 4.2; 95 % CI: 1.7–10.2; p <0.01)." (PMID 26718096, 2015). "Another study examined the relation between risk of statin-induced myopathy and genetic polymorphism in the vitamin D receptor (VDR)." (PMID 26718096, 2015). "The dysregulation of nuclear receptors, such as VDR and RXRα in muscle cells, has also been postulated to result in myopathy via their effects on muscle structural integrity and metabolism." (PMID 24782788, 2014). "In vitro cell culture models, in vivo rodent models as well as clinical studies in humans are starting to clarify the mechanisms of vitamin D action mediated via the VDR in muscle in order to enhance our understanding of their role in inflammatory mediated myopathy and muscle weakness." (PMID 24782788, 2014).
psychiatric disorder (5 papers, 2012 to 2025). A disorder characterized by behavioral and/or psychological abnormalities, often accompanied by physical symptoms. "Three novel structural variants of the vitamin D receptor were reported in psychiatric disease." (PMID 22898564, 2012). "Common variants of the vitamin D receptor—FokI, BsmI, and TaqI—shape emotion and cognition in late life, while the BDNF Val66Met polymorphism alters neurotrophin secretion and susceptibility to mental illness." (PMID 40871684, 2025). "TRANSFAC analysis predicted potential alterations in transcription factor binding sites, including the abolishment of a binding site for the vitamin D receptor and the creation of an orthodenticle homeobox binding site (OTX), previously implicated in psychiatric disorders." (PMID 24720851, 2014).
retinopathy (5 papers, 2013 to 2025). "In the present study, the VDR ApaI and BsmI genotypes were associated with retinopathy in T2DM patients." (PMID 36143273, 2022). "We did not study genetic risk factors in our study; thus, we cannot exclude the possibility that VDR gene polymorphisms is a confounder for other factors contributing to retinopathy in adults with DM2." (PMID 24251044, 2013). "This suggests the possibility that the VDR variants ApaI C > A and BsmI C > T could be used as genetic biomarkers for retinopathy and HDL levels among T2DM patients of Jordanian Arabic origin." (PMID 36143273, 2022). "Therefore, the increased risk of retinopathy among patients with VDR ApaI and BsmI variant alleles may be related to the significant variation in HDL levels." (PMID 36143273, 2022). "We found that the VDR rs7975232 and rs1544410 alleles were significantly (p = 0.008–0.04) associated with high-density lipoprotein (HDL) levels and retinopathy among patients." (PMID 36143273, 2022). "The VDR variants ApaI A > C and BsmI C > T were significantly associated with HDL levels and retinopathy." (PMID 36143273, 2022). "The VDR ApaI and BsmI genotypes are associated with HDL levels and retinopathy among T2DM patients of Jordanian Arabic origin." (PMID 36143273, 2022). "Therefore, we concluded that the VDR rs7975232 and rs1544410 alleles were associated with HDL levels and retinopathy and can be considered as potential genetic biomarkers for the lipid profile and retinopathy complication among T2DM patients in a Jordanian population of Arabic origin." (PMID 36143273, 2022).
benign tumors (4 papers, 2015 to 2025). "This study aims to analyze differences in immunostaining intensity for CD44, CD133, and VDR among groups of benign tumors, low-grade atypical proliferative tumors, and five distinct malignant phenotypes (HGSC and non-HGSC)." (PMID 40332380, 2025). "VDR mRNA and protein levels were lower in ACCs than in benign tumors, and VDR immunostaining was weak or negative in ACCs, including all 3 methylated tissue samples." (PMID 26843863, 2015).
endocrine disorders (3 papers, 2020 to 2025). "In the Romanian population, VDR polymorphism research was primarily focused on dental and endocrine disorders." (PMID 41301713, 2025). "Collectively, these studies imply that rs1544410 in VDR may be a genetic marker for endocrine disorders." (PMID 36046800, 2022).
neurodevelopmental disorder (2 papers, 2023 to 2025). A behavioral and cognitive disorder with onset during the developmental period that involves impaired or aberrant development of intellectual, motor, or social functions. "Vitamin D/Vitamin D receptor does have a protective effect on the nervous system of the brain and also regulates the gut microbiota, and VDR is indirectly linked to neurodevelopmental disorders through the gut brain axis." (PMID 37007507, 2023). "Variants in the VDR gene have been associated with neurodevelopmental disorders." (PMID 41340975, 2025).
respiratory disease (2 papers, 2014 to 2016). "Ethnic-specific genetic or cultural factors may enhance or abolish the effects of VDR polymorphisms on host susceptibility to respiratory diseases such as TB." (PMID 26894582, 2016).
gastrointestinal disease (1 paper, 2021). A disease that occurs in the gastrointestinal system, excluding the hepatobiliary system. "Gut epithelial vitamin D receptor (VDR) signaling appears to play an essential role in controlling mucosal inflammation and thus could be a useful therapeutic target in the management of some gastrointestinal diseases." (PMID 34881266, 2021).
parathyroid gland (1 paper, 2020). "The persistence of these triggers leads to a progressive reduction of calcium-sensing receptors (CaSR) and vitamin D receptors (VDR) expression in parathyroid glands preluding to irreversible parathyroid gland hyperplasia onset." (PMID 32120854, 2020).
skeletal muscle disorder (1 paper, 2017). A disease involving the skeletal muscle tissue. "It is also worth citing that a relationship between VDR activation and skeletal muscle disorders has already been reported." (PMID 28423519, 2017).
VDR also shares sentences with these, for which no sentence is quoted: chronic periodontitis (13 papers); end-stage renal disease (8); Parkinson (6); Uterine leiomyoma (5); colorectal adenocarcinoma (4); essential hypertension (4); hypertrophy (4); hypoparathyroidism (4); vitamin deficiency (4); Abdominal obesity (3); congestive heart failure (3); gynecological diseases (3); idiopathic scoliosis (3); knee osteoarthritis (3); primary biliary cholangitis (3); ulcer (3); acute myocardial infarction (2); alopecia areata (2); amyotrophic lateral sclerosis (2); anorexia nervosa (2); Barrett esophagus (2); calcification (2); calcium oxalate kidney stones (2); cardiac arrhythmia (2); cerebrovascular diseases (2); Clear Cell Renal Cell Carcinoma (2); Cluster headache (2); Connective Tissue Diseases (2); diabetic foot ulcer (2); Diarrhea (2).
A further 188 diseases each share a sentence with VDR in 2 papers or fewer.